COPZ1 (coat protein complex I subunit zeta 1)
Description:
Component of the coatomer complex, involved in retrograde Golgi-to-ER transport. The coatomer is a cytosolic protein complex that binds to dilysine motifs and reversibly associates with Golgi non-clathrin-coated vesicles, which further mediate biosynthetic protein transport from the ER, via the Golgi up to the trans Golgi network. Coatomer complex is required for budding from Golgi membranes, and is essential for the retrograde Golgi-to-ER transport of dilysine-tagged proteins (By similarity). The zeta subunit may be involved in regulating the coat assembly and, hence, the rate of biosynthetic protein transport due to its association-dissociation properties with the coatomer complex (By similarity).
Synonyms: COPZ; CGI-120; HSPC181; SCN12; zeta-COP; zeta1-COP
Tractability: Antibody: UniProt places it where antibodies can reach, with medium confidence. PROTAC: ubiquitination databases record sites on it; its protein half-life has been measured.
Gene: Protein-coding gene on chromosome 12 (54,301,202 to 54,351,848, forward strand). Ensembl gene ENSG00000111481.
Subcellular location: Cytoplasm; Golgi apparatus membrane; Cytoplasmic vesicle, COPI-coated vesicle membrane
Pathways (Reactome):
Vesicle-mediated transport: COPI-dependent Golgi-to-ER retrograde traffic; COPI-mediated anterograde transport
Gene Ontology:
Biological process: intra-Golgi vesicle-mediated transport; retrograde vesicle-mediated transport, Golgi to endoplasmic reticulum; intracellular protein transport; vesicle-mediated transport
Cellular component: COPI vesicle coat; cytosol; endoplasmic reticulum membrane; Golgi membrane; transport vesicle; COPI-coated vesicle membrane; cytoplasm; membrane coat
Genetic constraint (gnomAD): Loss-of-function variants: 4 observed, 20.67 expected, observed/expected ratio (o/e) 0.19, 90% interval 0.094 to 0.44. The upper end of that interval is the gene's LOEUF score, 0.44, which puts it in group 1 of 6, group 1 being the genes least tolerant of losing a copy. Missense variants: 122 observed, 157.23 expected, observed/expected ratio (o/e) 0.78, 90% interval 0.67 to 0.9. Synonymous variants: 51 observed, 62.01 expected, observed/expected ratio (o/e) 0.82, 90% interval 0.66 to 1.04.
Homologues: Orthologues: chimpanzee COPZ1 (100% identical), mouse Copz1 (100% identical), guinea pig COPZ1 (99% identical), rabbit COPZ1 (99% identical), tropical clawed frog copz1 (93% identical), zebrafish copz1 (93% identical), pig COPZ1 (85% identical), rat Copz1 (76% identical), dog COPZ1 (67% identical), Drosophila melanogaster zetaCOP (59% identical), Caenorhabditis elegans copz-1 (54% identical). Paralogues in human: COPZ2 (73% identical).
Diseases named in the same sentence as COPZ1 in open-access papers:
COPZ1 is named in the same sentence as 32 diseases in open-access papers, as found by Europe PMC text mining. Sharing a sentence is not in itself a finding about the gene and the disease. The quoted sentences say what the papers report.
glioblastoma (11 papers, 2021 to 2025). The most malignant astrocytic tumor (WHO grade IV). "Knockdown of COPZ1 in a glioblastoma cell line led to the induction of autophagy and degradation of ferritin with subsequent ferroptosis." (PMID 39062119, 2024). "The result showed that except for the glioblastoma multiforme and esophageal carcinoma, COPZ1 had a positive correlation with the HIF1A in most of the rest cancer." (PMID 37107648, 2023). "For instance, the inhibition of coatomer protein complex subunit zeta 1 (COPZ1) leads to a decrease in glioblastoma (GBM) cell proliferation through the upregulation of NCOA4 and the facilitation of ferritin degradation." (PMID 38110359, 2023). "Loss of coatomer subunit zeta-1 (COPZ1) induces NCOA4-mediated autophagy and ferroptosis in glioblastoma cell lines." (PMID 38139106, 2023). "Zeta1 (COPZ1), the complex subunit of the coat protein, is a putative therapeutic target for glioblastoma, which can significantly affect iron metabolism and tumor prognosis." (PMID 36160450, 2022). "On the contrary, coatomer protein complex subunit zeta 1 (COPZ1) was identified as a promising target for glioblastoma treatment, involving iron metabolism as a critical component of the COPZ1/NCOA4/FTH1 axis, manifesting a negative regulation of expression and activity of NCOA4." (PMID 38961066, 2024). "Therefore, COPZ1 is considered a new therapeutic target for the treatment of human glioblastomas." (PMID 39062119, 2024). "A large body of evidence demonstrates the dependency of several tumors such as breast, prostate, ovary, thyroid, glioblastoma and LUAD, on the activity of COPZ1, a component of the heptameric COPI complex." (PMID 40978486, 2025). "Knockdown of COPZ1 can induce ferritinophagy by increasing NCOA4 and ATG7 expression levels in glioblastoma cells." (PMID 38961066, 2024). "Given the already known role of NCOA4 in ferritin degradation, targeting the COPZ1/NCOA4/FTH1 axis may be a promising therapeutic strategy for the treatment of human glioblastoma (GBM)." (PMID 35756082, 2022). "In contrast, COPZ1 (coatomer protein complex subunit zeta 1) inhibits NCOA4 expression, while silenced COPZ1 increases NCOA4 protein levels and promotes ferritinophagy in glioblastoma multiforme." (PMID 36289191, 2022).
thyroid tumor (6 papers, 2015 to 2025). A benign or malignant neoplasm affecting the thyroid gland. "Several studies have reported that COPZ1 is vital for sustaining cancer cell survival in thyroid tumors, breast cancer, ovarian cancer, and prostate cancer." (PMID 37107648, 2023). "In thyroid tumor cells, depletion of COPZ1 leads to cell death, suggesting it has potential as a therapeutic target for thyroid cancer, furthermore, subcutaneous xenograft models locally injected with siRNAs against COPZ1 reduced thyroid tumor growth." (PMID 33420375, 2021). "Depletion of COPZ1 can lead to thyroid tumor cell death both in vitro and in vivo." (PMID 37107648, 2023). "Our screening and validation identified COPZ1 as a thyroid tumor cell specific survival gene." (PMID 26431489, 2015). "Further analysis of three selected hit genes, namely Cyclin D1, MASTL and COPZ1, showed that they represent common vulnerabilities for thyroid tumor cells, as their inhibition reduced the viability of several thyroid tumor cell lines, regardless the histotype or oncogenic lesion." (PMID 26431489, 2015). "Interestingly, we found that silencing of Cyclin D1, MASTL and COPZ1 inhibits the growth of several further thyroid tumor cell lines." (PMID 26431489, 2015). "To assess whether the survival genes confirmed in BCPAP cells are involved in such common pathways, we investigated the effect of CCND1, MASTL and COPZ1 gene silencing in a panel of thyroid tumor-derived cell lines representative of different tumor histotypes." (PMID 26431489, 2015). "Whether the thyroid tumor cell dependency upon COPZ1 is related to downregulation of COPZ2 isoform, or to deregulation of other COPI components, as well as the modalities through which COPZ1 inhibition leads to growth suppression of thyroid tumor cells, remains to be investigated." (PMID 26431489, 2015). "By screening a siRNA library, we identified COPE and COPZ1 among a set of genes whose silencing inhibited the growth of a panel of thyroid tumor cells, but not of normal immortalized thyrocytes." (PMID 40978486, 2025). "As for Shtutman study, thyroid tumors showed frequent downregulation of the paralog COPZ2 gene; these findings allowed us to speculate that the majority of TC may be eligible for COPZ1 targeting." (PMID 40978486, 2025).
glioma (4 papers, 2021 to 2023). A benign or malignant brain and spinal cord tumor that arises from glial cells (astrocytes, oligodendrocytes, ependymal cells). "In this work, we analyzed genomic datasets for human glioma and discovered that high expression of COPZ1 was associated with poor prognosis and increasing tumor malignancy." (PMID 33420375, 2021). "Overexpression of COPZ1 was associated with increasing tumor grade and poor prognosis in glioma patients based on analysis of expression data from the publicly available database The Cancer Genome Atlas (P < 0.001)." (PMID 33420375, 2021). "Taken together, these results indicate that COPZ1 may have an important role in glioma progression and serve as a novel diagnostic marker." (PMID 33420375, 2021). "In this context, Zhang and collaborators revealed that the overexpression of the Coatomer protein complex subunit zeta 1 (COPZ1), a component of the coatomer protein complex I, was associated with increasing tumor grade and poor prognosis in glioma patients." (PMID 35805884, 2022). "The results showed that COPZ1 expression was positively associated with tumor grade and liquefactive necrosis, independent from age, gender, tumor size, and edema, which suggested that COPZ1 could be a potential diagnostic marker for glioma patients (p < 0.05)." (PMID 33420375, 2021). "To begin to examine the role of COPZ1 in the development of human glioma, we first examined mRNA levels of the gene in human glioma samples using the expression data in the publicly available dataset from The Cancer Genome Atlas (TCGA)." (PMID 33420375, 2021). "Finally, western blot analysis demonstrated that COPZ1 protein levels were also elevated in human glioma cells U87MG, U251, A172, LN229, T98 and P3#GBM relative to normal human astrocytes (NHA) in culture." (PMID 33420375, 2021). "Thus, the COPZ1/NCOA4/FTH1 axis may be a novel therapeutic target in the treatment of gliomas." (PMID 33420375, 2021). "COPZ1 mRNA levels were increased in low grade (WHO II; n = 226) and high-grade gliomas (WHO III, n = 244; WHO IV, n = 150; p < 0.0001) relative to non-neoplastic brain tissue samples (n = 4)." (PMID 33420375, 2021). "We found a corresponding increase in COPZ1 protein levels in western blot analysis of lysates prepared from primary human glioma specimens relative to non-neoplastic brain tissue samples (~4×, grade IV vs non-neoplastic tissue samples)." (PMID 33420375, 2021).
thyroid cancer (4 papers, 2015 to 2023). "Collectively, our study identified Cyclin D1, MASTL and COPZ1 as thyroid cancer cell specific vulnerabilities, suggesting that they could provide a common therapeutic target in thyroid cancer treatment." (PMID 26431489, 2015). "Thus we envisage that Cyclin D1, MASTL and COPZ1 are attractive targets for new therapeutic approaches for thyroid cancer which spare normal cells and which would thus have limited side effects." (PMID 26431489, 2015). "Besides, Silencing COPZ1 causes the endoplasmic reticulum (ER) stress to increase and the type I IFN pathway activated, and then promotes the secretion of a variety of inflammatory molecules and enhances anti-tumor immunity in thyroid cancer." (PMID 37107648, 2023). "We next performed some experiments to further corroborate the dependency of thyroid cancer cells upon Cyclin D1, MASTL and COPZ1 activity." (PMID 26431489, 2015). "However, we found that COPZ1 with a lower expression level in kidney chromophobe (KICH) and thyroid carcinoma (THCA) compared with normal tissues." (PMID 37107648, 2023).
liver cancer (3 papers, 2020 to 2023). An epithelial or non-epithelial malignant neoplasm that arises from the liver. "Finally, we validated the role of the COPZ1 on the tumor growth and migration in the liver cancer with the biological experiments." (PMID 37107648, 2023). "In tumor tissue compared to healthy tissue, the amount of COPZ1 protein expression was noticeably increased in breast cancer, colon cancer, OV, UCEC, lung cancer, HNSC and liver cancer." (PMID 37107648, 2023). "Compared to the normal tissues, we discovered that numerous cancer types have significant levels of COPZ1 mRNA expression, and the COPZ1 protein expression level was considerably greater in breast cancer, colon cancer, OV, UCEC, lung cancer, HNSC and liver cancer tissues." (PMID 37107648, 2023). "A recent study showed that the expressions of COPZ1 and EFTUD2 were significantly higher in tumor tissues compared with normal tissues and both two genes may correlated with poor prognosis of liver cancer based on the TCGA database." (PMID 34257558, 2021).
breast carcinoma (2 papers, 2023 to 2026). "Additionally, BMI1 can promote breast cancer cell proliferation and inhibit autophagy by activating COPZ1 transcription." (PMID 37107648, 2023). "Previous research has demonstrated that COPZ1 is indispensable for many types of cancer since the cancer cell possessed a low expression of the isoform COPZ2, including breast cancer, ovarian cancer, and prostate cancer." (PMID 37107648, 2023).
cognitive decline (2 papers, 2015 to 2018). "Collectively, we report the association of three RNA biomarkers, COPZ1, EFTUD2 and PTBP1 with clinical features including cognitive decline in early drug-naïve PD patients." (PMID 26566043, 2015). "In addition, COPZ1 and EFTUD2 have been associated with cognitive decline in PD patients." (PMID 29896099, 2018). "Discriminant analysis showed that the best predictors of cognitive decline were EFTUD2, COPZ1, PTPN1, FAXDC2, MLST8 and age." (PMID 29896099, 2018).
Cognitive impairment (2 papers, 2015 to 2018). Abnormal cognition is characterized by deficits in thinking, reasoning, or remembering. "In addition, the combination of PTPN1, COPZ1, FAXDC2, EFTUD2 and MLST8 is a useful signature for cognitive impairment." (PMID 29896099, 2018).
lung carcinoma (2 papers, 2021 to 2023). "In lung cancer, a study reported that HIF1A could mediate the immunosuppressive by the HIF1A/LOXL2/EMT pathways, and our results also showed that COPZ1 had a positive correlation with HIF1A, LOXL2 and EMT." (PMID 37107648, 2023).
Parkinson (2 papers, 2015 to 2016). "Further, COPZ1, EFTUD2 and PTBP1 mRNAs correlated with clinical features in PD patients including the Hoehn and Yahr scale, Movement Disorder Society revision of Unified Parkinson’s Disease Rating Scale (MDS-UPDRS) and Montreal Cognitive Assessment (MoCA) score." (PMID 26566043, 2015).
Alzheimer disease (1 paper, 2015). A progressive, neurodegenerative disease characterized by loss of function and death of nerve cells in several areas of the brain leading to loss of cognitive function such as memory and language. "Impairment of intracellular trafficking has been implicated in the pathogenesis of Alzheimer’s disease, so COPZ1 may be associated with Alzheimer’s disease." (PMID 26399914, 2015).
amyotrophic lateral sclerosis (1 paper, 2012). Amyotrophic lateral sclerosis (ALS) is a neurodegenerative disease characterized by progressive muscular paralysis reflecting degeneration of motor neurons in the primary motor cortex, corticospinal tracts, brainstem and spinal cord. "Copz1 and map4k1 are also dysregulated in amyotrophic lateral sclerosis patients." (PMID 22952715, 2012).
endometrial cancer (1 paper, 2023). Primary or metastatic malignant neoplasm involving the endometrium (mucous membrane that lines the endometrial cavity). "According to the findings, endometrial cancer had the highest frequency of COPZ1 alterations, the majority of which were amplification mutations." (PMID 37107648, 2023).
enterovirus infection (1 paper, 2024). "The mechanistic elucidation of MPA-CF3 against EV-A71 may offer an alternative COPZ1-involved therapeutic pathway for enterovirus infection." (PMID 38840773, 2024).
pancreatic cancer (1 paper, 2023). "In pancreatic cancer, the albumin level of COPZ1 was lower in tumor tissue when compared to normal tissue." (PMID 37107648, 2023).
tumor (17 papers, 2014 to 2025). "In different tumor models COPZ1 inhibition was found implicated in abortive autophagy, ER stress and activation of ferroptosis." (PMID 40978486, 2025). "With respect to COPZ1, the susceptibility to its inhibition is related to the tumor-specific downregulation of the paralog gene COPZ2." (PMID 40978486, 2025). "Together, these findings demonstrated that loss of COPZ1 inhibited GBM tumor growth possibly through ferroptosis mediated tumor cell death." (PMID 33420375, 2021). "Moreover, they showed that COPZ1 dependency is caused by the tumor-specific downregulation of the paralog gene encoding the COPZ2 isoform, thus introducing the concept of paralog dependency." (PMID 40978486, 2025). "Coatomer Protein Complex, Subunit Zeta 1 (COPZ1) is associated with increased tumour grade." (PMID 34099897, 2021). "Two important issues emerged from this study: 1) COPZ1 fits both canonical and paralog dependency definitions; 2) the downregulation of the paralog COPZ2 gene can predict the tumor response to COPZ1 inhibition." (PMID 40978486, 2025). "In this review we summarize the different studies characterizing COPZ1 as a NOA gene in different tumor types, and discuss potential issues related to its targeting." (PMID 40978486, 2025). "This was documented by us in TC preclinical models, but in other COPZ1-addicted tumor types remains to be investigated." (PMID 40978486, 2025). "We demonstrated the efficacy of COPZ1 depletion in in vivo preclinical setting: in TC cells mouse xenografts local treatment with siRNAs targeting COPZ1 reduces tumor growth." (PMID 40978486, 2025). "Mounting evidence support COPZ1 as a NOA gene in different tumor types, proposing it as a potential novel therapeutic targets for tumors of different origin." (PMID 40978486, 2025). "We report different evidence supporting COPZ1 as a NOA gene in different tumor type; we discuss potential issues related to its targeting." (PMID 40978486, 2025). "A similar interplay between COPZ1 and NCOA4 and ferroptosis has also been reported in LUAD, a tumor type in which high expression of COPZ1 was indicative of malignancy and poor overall survival." (PMID 40978486, 2025). "COPZ1 has a specifically shortened 3′UTR in pDCs and is associated with immune cell infiltration and pro-inflammatory cytokines in tumor cells." (PMID 38982223, 2024). "We further assessed the differential protein expression of COPZ1 between tumor and normal tissue in the Clinical Proteomic Tumor Analysis Consortium (CPTAC) dataset." (PMID 37107648, 2023). "Since the pathway enrichment results indicated that COPZ1 was correlated with many immune response pathways, we wanted to find out how COPZ1 expression related to the tumor microenvironment and immunomodulator expression." (PMID 37107648, 2023). "Our works revealed the prognosis value of COPZ1 in a variety of cancers and its correlation with stemness score, hypoxia score and tumor immune microenvironment." (PMID 37107648, 2023). "We found that the mRNA level of COPZ1 was significantly higher in HCC tissues than the adjacent non-tumor tissue both in GSE17856 and GSE14520 datasets, which was similar to the result generated by TCGA dataset." (PMID 37107648, 2023). "Next, we performed a methylation analysis of the COPZ1 promoter region, and we found that there were differences in the methylation of the COPZ1 promoter region between normal and tumor tissues." (PMID 37107648, 2023). "Since stemness and hypoxia are two important features of tumors, we next investigated how the tumor’s stemness and hypoxia index were related to COPZ1 expression." (PMID 37107648, 2023). "Considering that the TFs which promote the expression of COPZ1 should exert the same expression pattern as COPZ1, we selected the TFs which were upregulated in tumor tissues for further analysis." (PMID 37107648, 2023). "We firstly performed differential expression analysis of COPZ1 transcription factors between normal and tumor tissues." (PMID 37107648, 2023).